UCN2 (urocortin 2)
Description:
Hormone that plays a central role in whole body adaptation to stress. Released by the hypothalamus primarily in response to physical or psychological stress and acts by binding to CRH receptor CRHR2. UCN2-dependent signaling regulates cardiovascular function, promotes skeletal muscle hypertrophy and manage energy balance and acts as an anorexigenic agent (By similarity). In contrast to CRH and UCN, does not activate the hypothalamus-pituitary-adrenal axis to promote corticotropin hormone (ACTH) production.
Synonyms: SRP; URP; UCNI; UCN-II; UR
Tractability: Antibody: its Gene Ontology location is reachable by antibodies, with high confidence; UniProt places it where antibodies can reach, with medium confidence; UniProt predicts a signal peptide or a membrane-spanning region.
Gene: Protein-coding gene on chromosome 3 (48,561,718 to 48,563,781, reverse strand). Ensembl gene ENSG00000145040.
Subcellular location: Secreted
Subcellular location (Human Protein Atlas): Vesicles; Predicted to be secreted
Pathways (Reactome):
Signal Transduction: Class B/2 (Secretin family receptors)
Gene Ontology:
Molecular function: neuropeptide hormone activity; corticotropin-releasing hormone receptor binding; corticotropin-releasing hormone receptor 2 binding; G protein-coupled receptor binding; hormone activity
Biological process: adenylate cyclase-activating G protein-coupled receptor signaling pathway; cellular response to nutrient levels; general adaptation syndrome; hormone-mediated signaling pathway; negative regulation of insulin receptor signaling pathway; digestion; negative regulation of vasculogenesis
Cellular component: extracellular region
Genetic constraint (gnomAD): Loss-of-function variants: 3 observed, 1.9 expected, observed/expected ratio (o/e) 1.58, 90% interval 0.58 to 1.93. That is too few expected variants to judge how well the gene tolerates losing a copy. Missense variants: 127 observed, 140.85 expected, observed/expected ratio (o/e) 0.9, 90% interval 0.78 to 1.04. Synonymous variants: 64 observed, 60.42 expected, observed/expected ratio (o/e) 1.06, 90% interval 0.87 to 1.3.
Homologues: Orthologues: macaque UCN2 (91% identical), pig UCN2 (69% identical), mouse Ucn2 (60% identical), zebrafish ucn3l (24% identical), tropical clawed frog ucn3 (22% identical). Paralogues in human: UCN3 (21% identical).
Diseases named in the same sentence as UCN2 in open-access papers:
UCN2 is named in the same sentence as 55 diseases in open-access papers, as found by Europe PMC text mining. Sharing a sentence is not in itself a finding about the gene and the disease. The quoted sentences say what the papers report.
Anxiety (8 papers, 2010 to 2025). Intense feelings of nervousness, tension, or panic often arise in response to interpersonal stresses. "Crhr2 upregulation can also be linked to anxiety, as urocortin 2 (a CRHR2 agonist) induced anxiety-like behavior, when injected into the medial amygdala in rats." (PMID 37989901, 2024). "A further reduction in anxiety-like behavior was observed after double Ucn1/Ucn2 deficient mice were exposed to acute stress, and this reduction in anxiety was correlated with levels of serotonin in anxiety-related brain regions." (PMID 23487366, 2013). "Animals with CRHR2 knockout or that of its ligands (Ucn2 KO and Ucn3 KO) display increased anxiety, corticosterone response, and impaired stress recovery." (PMID 39595978, 2024). "Previous studies have shown that the effect of Ucn2 on anxiety-like behavior is highly variable and differs depending on the level of stress or the brain regions involved." (PMID 39595978, 2024). "In the nicotine withdrawal model, ICV administration of Ucn2 and Ucn3 ameliorated anxiety- and depressive-like behavior in mice, but it is important to note that behavioral testing was performed 30 min after the ICV application." (PMID 39595978, 2024). "Ucn1/Ucn2 dKO mice display reduced basal anxiety as well as reduced stress-induced anxiety in the OF and LD tests." (PMID 23077729, 2012). "The EPM test was performed to examine whether CRHR2 agonist (Ucn2 or Ucn3) treatment could prevent the development of anxiety-like behavior in the SPS animals compared to the vehicle-treated ones." (PMID 39595978, 2024). "Moreover, they also showed that the central administration of Ucn2 or Ucn3 has the potential to ameliorate anxiety- and depressive-like behavior." (PMID 39595978, 2024). "Indeed, two recent studies have highlighted the role of leptin and urocortin 2 signaling in the brain as sites of action that modulate thermal nociception and anxiety-like behavior, respectively." (PMID 20604941, 2010). "In addition, behavioral studies focused on the UCN2 peptide demonstrated that intracerebroventricular (ICV) administration of UCN2 in mice and rats produced high levels of anxiety responses, which correlated with an increase in c-Fos expression in DRN-5-HT neurons projecting to the PVN." (PMID 41009573, 2025). "The activation of CRF1 by the intracerebroventricular (ICV) injection of CRF and Ucn1 evokes the activation of the HPA axis, as well as anxiety-like and depression-like behavior, whereas activation of CRF2 by the ICV administration of Ucn2 and Ucn3 has anxiolytic and antidepressant effects in rats." (PMID 37626714, 2023). "Behaviorally, Ucn2 KO mice show no anxiety phenotypes but the females do display less despair in the FST and TST tests." (PMID 23077729, 2012). "However, the ICV administration of Ucn1, Ucn2, and Ucn3 in mice, and the global knock-out of urocortins and their receptors led to different results regarding the activation of the HPA-axis, as well as for anxiety- and depression-like behavior." (PMID 37626714, 2023). "Ucn2 knockout mice have revealed no significant changes in anxiety-like behavior." (PMID 23487366, 2013).
heart failure (8 papers, 2012 to 2024). Inability of the heart to pump blood at an adequate rate to meet tissue metabolic requirements. "Other notable candidate genes with loss of H3K27me3 occupancy are ABCB9 (associated with type 2 diabetes); Sts (associated with HF diet and ob/ob models of obesity and type 2 diabetes); and Ucn2 (associated with heart failure patients)." (PMID 28425976, 2017). "A recent systemic meta-analysis of 42 clinical trials shows that short-term UCN2 infusion can reduce mean arterial pressure and reduced ejection fraction, making it a promising therapy for heart failure." (PMID 37860766, 2023). "The findings from a study that ascertained the effects of UCN2 in male rats with heart failure reveal that increased CRF2 receptor expression in the heart is correlated with a higher survival rate, without aggravating stress-related behavior." (PMID 32244319, 2020). "To date, most studies into urocortins have focused on UCN1 and UCN2 in various diseases including heart failure (HF) and have revealed compelling data on the endogenous compensatory role of UCN1 and UCN2 and their cardioprotective effects." (PMID 31781037, 2019). "Adjunct Ucn2 therapy with diuretics in heart failure is beneficial, because Ucn2 administration induces sustained improvements in hemodynamics and renal function, in association with inhibition of multiple vasoconstrictor/volume-retaining systems." (PMID 22654906, 2012). "For acutely decompensated heart failure patients, UCN2 infusion leads to decreased systolic blood pressure, a reduction in total peripheral resistance, and increased cardiac output with a nonsignificant elevation in heart rate when compared to the placebo group." (PMID 31935997, 2020). "UCN2 when injected peripherally acting via CRF2 raises left ventricular ejection fraction and cardiac output levels in the treatment of heart failure patients, corresponding with a decrease in vascular resistance." (PMID 32244319, 2020). "UCN2 and UCN3 are expressed in the heart and may have beneficial effects on cardiovascular pathophysiology, particularly heart failure (HF)." (PMID 31935997, 2020).
Obesity (4 papers, 2017 to 2023). Accumulation of substantial excess body fat. "The sum of the central effects of Ucn2 on energy metabolism changes with aging way suggest a role for this peptide in the development of both middle-aged obesity and aging anorexia and hypermetabolism leading to cachexia." (PMID 37240340, 2023). "Knockout mice for Ucn2 or Crfr2 are resistant to diet-induced obesity and Ucn2 knockouts have increased muscle mass." (PMID 30717377, 2019). "Based on these characteristics, Ucn2 may be a worthy target of investigation in the search for anti-obesity drugs." (PMID 37240340, 2023). "Ucn2 shows potential in the prevention of middle-aged obesity." (PMID 37240340, 2023). "Our results suggest that Ucn2 would not be an effective treatment for middle-aged obesity, since it fails to induce anorexia or weight loss in the older middle-aged group." (PMID 37240340, 2023). "Our results show that age-dependent changes in Ucn2 may contribute to middle-aged obesity and aging cachexia." (PMID 37240340, 2023). "We aimed to study the role of Ucn2 in middle-aged obesity and aging cachexia." (PMID 37240340, 2023). "Overall, significant negative correlations were observed for UCN1 expression and obesity markers (BMI, percentile, body fat percentage, and cholesterol), for UCN3 and TNFα and NGAL, as well as for CRH and TNFα, RBP4, ZAG, and circulating UCN2 levels (p < 0.05)." (PMID 35276788, 2022).
Hypertension (3 papers, 2012 to 2018). The presence of chronic increased pressure in the systemic arterial system. "Nevertheless, other reports suggested an anti-hypertrophic action of chronic infusion of Ucn-2 in a rat model of arterial hypertension and in mice model of heart infarct." (PMID 30018568, 2018). "Long-term Ucn2 treatment in hypertensive rats induces sustained blood pressure reduction and diminishes the development of hypertension-induced left ventricular hypertrophy and the deterioration of left ventricular contractile function." (PMID 22654906, 2012). "Together, CRF2 receptor stimulation by Ucn2 may represent a novel approach to the treatment of arterial hypertension." (PMID 22654906, 2012).
Insulin resistance (3 papers, 2019 to 2023). Increased resistance towards insulin, that is, diminished effectiveness of insulin in reducing blood glucose levels. "In the current study, acute UCN2 dosing agonizes CRHR2 causing insulin resistance in the skeletal muscle, whereas chronic, elevated levels of UCN2 desensitize CRHR2 leading to the opposite: insulin sensitization." (PMID 37402735, 2023). "ITTs demonstrated that increasing doses of UCN2 gave rise to decreasing rates of glucose uptake in response to insulin injection, confirming that acute UCN2 causes insulin resistance in vivo." (PMID 37402735, 2023). "Ucn2 gene transfer altered metabolites in liver that are associated with glucose metabolism and insulin resistance in HFD mice—restoring key metabolites to normal levels." (PMID 31790421, 2019). "AAV8.Ucn2 gene transfer was associated with increased insulin sensitivity, reduced hyperglycemia and fatty liver in mice that developed insulin resistance." (PMID 31790421, 2019). "Intravenous (IV) delivery of an adeno-associated virus vector serotype 8 encoding Ucn2 (AAV8.Ucn2) increases insulin sensitivity and glucose disposal in mice with insulin resistance." (PMID 31790421, 2019). "Here we show that acute dosing of UCN2 induces systemic insulin resistance in male mice and skeletal muscle." (PMID 37402735, 2023). "Recently, UCN2 has been shown to promote skeletal muscle health, and gene transfer of UCN2 results in reduced fatty infiltration of the liver in mice with insulin resistance, proposing their potential beneficial role in type 2 diabetes treatment." (PMID 37860766, 2023). "UCN2 and modified UCN2 peptides have been proposed as potential pharmaceutical treatments for insulin resistance in skeletal muscle." (PMID 37402735, 2023). "The circulating levels of UCN2 reported in murine models of insulin resistance and in human patients with increased HOMA-IR fall in the range where we would expect to see mostly Gs recruitment to CRHR2 and very little alternative activation." (PMID 37402735, 2023). "Given the published effects that UCN2 and UCN3 have on insulin signaling, we began by investigating circulating UCN2 and UCN3 levels in established genetic models of insulin resistance." (PMID 37402735, 2023).
Anorexia (2 papers, 2013 to 2023). Lack of desire to eat (loss of appetite). "Our observations with regard to age-dependent changes in Ucn2-induced anorexia and weight loss are in accordance with the literature data that show a complex relationship between hypothalamic anorexigenic mediators." (PMID 37240340, 2023). "Ucn2-induced anorexia was long-lasting; it remained significant for 7 days in the young adult 3-month-old group, for 14 days in the 6-month-old younger middle-aged group, and for 2 days in the oldest 18-month-old group." (PMID 37240340, 2023). "Following one central injection, Ucn2-induced anorexia lasted for 9 days in the 3-month, 14 days in the 6-month and 2 days in the 18-month group." (PMID 37240340, 2023). "Urocortin 2 is a specific ligand of CRF-2 receptors and has been implicated in mediation of autonomic effects of stress, including anorexia." (PMID 23805290, 2013). "It seems that anorexia predominantly determines weight loss, since 12-month-old rats that showed a strong hypermetabolic response to Ucn2, but no anorexia, failed to lose weight." (PMID 37240340, 2023). "With regard to the anorexigenic effects, an acute ICV injection of Ucn2 reduced food intake in the 3-, 6- and 18-month-old groups, but failed to induce anorexia in the middle-aged 12-month-old animals." (PMID 37240340, 2023). "It is well-known that centrally applied Ucn2 elicits anorexia and hyperthermia via activation of the central CRH type 2 receptors We hypothesized that the responsiveness to Ucn2 changes during the course of aging, similarly to other catabolic mediators, such as leptin or alpha-MSH." (PMID 37240340, 2023).
chronic heart failure (2 papers, 2016 to 2018). "Actually, recent reports showed that Ucn-2 administration improved left ventricle contractility in patients with decompensated or chronic heart failure." (PMID 30018568, 2018).
colitis (2 papers, 2016 to 2019). Inflammation of the colon. "rWAS exposure increased the gene expression levels of IFN-γ, UCN2 and CRHR2 in LI-LPMCs; however, there was no sign of colitis in C57BL/6 mice." (PMID 27500935, 2016).
colorectal cancer (2 papers, 2013 to 2018). A primary or metastatic malignant neoplasm that affects the colon or rectum. "Stress has been proposed to be a tumor promoting factor through the secretion of specific neuromediators, such as Urocortin2 and 3 (Ucn2/3), however its role in colorectal cancer (CRC) remains elusive." (PMID 24260200, 2013). "However, previous studies found that the dysregulation of UCN2/CRFR2 signaling was associated with prostate cancer, non-small cell lung carcinoma, colorectal cancer (CRC), Lewis lung carcinoma (LLC), and human adrenal and ovarian tumors." (PMID 29499655, 2018).
Glucose intolerance (2 papers, 2020 to 2023). Glucose intolerance (GI) can be defined as dysglycemia that comprises both prediabetes and diabetes. "Oral glucose tolerance tests (oGTTs) performed twenty minutes after UCN2 injection showed that mice treated with UCN2 displayed glucose intolerance, with highly elevated glucose levels two hours after the glucose bolus." (PMID 37402735, 2023). "We monitored glucose homeostasis in response to CRHR2 activation by UCN2 and, strikingly, found that acute treatment of UCN2 induces glucose intolerance in mice, while chronic treatment of UCN2 improves glucose tolerance." (PMID 37402735, 2023). "Blocking the endogenous CRHR2 agonist during gestation induces a mild glucose intolerance rather than overt gestational diabetes suggesting that UCN2 may act in concert with other placental signals to fine-tune the compensatory β-cell adaptations to maternal insulin resistance during pregnancy." (PMID 32106091, 2020).
preeclampsia (2 papers, 2024 to 2025). Preeclampsia is a hypertensive disorder of pregnancy that is characterized by new-onset hypertension with proteinuria presenting after 20 weeks of gestation, and depending on mild or severe forms may initially present with severe headache, visual disturbances, and hyperreflexia. "Alterations in UCN2 expression during immune and cellular stress responses are closely associated with pregnancy outcomes such as preterm birth and preeclampsia." (PMID 41329780, 2025). "In the hypoxic-ischemic environment of preeclampsia, a novel member of the CRH peptide family significantly increases Ucn2 and Ucn3, further promoting the response to oxidative stress in the placenta." (PMID 38894741, 2024).
breast carcinoma (1 paper, 2023). "However, there is evidence that the UCN2 pathway can upregulate VitD3 receptor expression in breast cancer as a pro-apoptotic mechanism, indicating the existence of a positive feedback loop that may also be relevant in the cutaneous environment." (PMID 37860766, 2023).
cardiac arrest (1 paper, 2021). Cessation of breathing and/or cardiac function. "In another preclinical cardiac arrest model, the intravenous (i.v.)administration of Ucn2 (10 μg/kg) upon the onset of resuscitation ameliorated left ventricular systolic and diastolic functions and cardiac output, while it decreased cardiomyocyte apoptosis assessed by TUNEL assay." (PMID 34829997, 2021). "Ucn2 produced a significant increase in Akt, ERK, and STAT3 activation and phosphorylation in the myocardium after cardiac arrest and resuscitation." (PMID 34829997, 2021).
cardiac hypertrophy (1 paper, 2018). "Perhaps, Ucn-2 preserved the observed cardiac hypertrophy to maintain its compensatory effect at least in the early stage of heart remodeling." (PMID 30018568, 2018). "Altogether, these data indicate that the administration of Ucn-2 in reperfusion recovers significantly cardiac hemodynamic functions, reduces infarct size, attenuates fibrosis but it doesn’t prevent cardiac hypertrophy." (PMID 30018568, 2018). "Interestingly, intravenous infusion of Ucn-2 before heart’s reperfusion recovered significantly cardiac contractility and prevented fibrosis, but it didn’t affect cardiac hypertrophy." (PMID 30018568, 2018). "In contrast, Ucn-2 didn’t inhibit I/R-induced cardiac hypertrophy." (PMID 30018568, 2018).
Cognitive impairment (1 paper, 2023). Abnormal cognition is characterized by deficits in thinking, reasoning, or remembering. "The cognitive impairment in NOR test correlated with mRNA expression of AgRP, not Ucn2, in the present study." (PMID 37168929, 2023).
depression (1 paper, 2023). "Based on the original, dualistic hypothesis, generalized anxiety disorder and major depression disorder could be treated by the inhibition of CRF1 with selective antagonists, such as antalarmin, or via the activation of CRF2 with selective agonists, such as Ucn2 or Ucn3." (PMID 37626714, 2023).
diabetes (1 paper, 2020). "Islets lacking UCN3 show increased insulin secretion and the exogenous administration of UCN2 normalized glucose levels in two distinct murine models of diabetes and increased glucose uptake in the skeletal muscles of obese mice." (PMID 32244319, 2020). "Recent evidence from experimental models of diabetes suggests that urocortin 2 and 3 (UCN2–3) might be involved in the regulation of insulin secretion and blood glucose levels." (PMID 32244319, 2020). "The role of UCN2 and UCN3 in glucose homeostasis and diabetes is emerging, whereas CRF2, the predominant peripherally expressed receptor, is a key mediator of sexually dimorphic responses in diabetes phenotype." (PMID 32244319, 2020).